SPDEF (SAM pointed domain containing ETS transcription factor)
Description:
May function as an androgen-independent transactivator of the prostate-specific antigen (PSA) promoter. Binds to 5'-GGAT-3' DNA sequences. May play a role in the regulation of the prostate gland and/or prostate cancer development. Acts as a transcriptional activator for SERPINB5 promoter.
Synonyms: PDEF; bA375E1.3
Tractability: No criterion of Open Targets' tractability assessment is met for any kind of drug.
Gene: Protein-coding gene on chromosome 6 (34,537,796 to 34,556,333, reverse strand). Ensembl gene ENSG00000124664.
Subcellular location: Nucleus
Subcellular location (Human Protein Atlas): Nucleoplasm; Cytosol; Nucleoli
Gene Ontology:
Molecular function: protein binding; sequence-specific DNA binding; sequence-specific double-stranded DNA binding; DNA-binding transcription factor activity, RNA polymerase II-specific; DNA-binding transcription factor activity
Biological process: negative regulation of transcription by RNA polymerase II; positive regulation of apoptotic process; cell differentiation; regulation of transcription by RNA polymerase II; regulation of DNA-templated transcription
Cellular component: chromatin; nucleus
Genetic constraint (gnomAD): Loss-of-function variants: 12 observed, 33.65 expected, observed/expected ratio (o/e) 0.36, 90% interval 0.23 to 0.58. The upper end of that interval is the gene's LOEUF score, 0.58, which puts it in group 2 of 6, group 1 being the genes least tolerant of losing a copy. Missense variants: 388 observed, 456.61 expected, observed/expected ratio (o/e) 0.85, 90% interval 0.78 to 0.92. Synonymous variants: 205 observed, 191.15 expected, observed/expected ratio (o/e) 1.07, 90% interval 0.96 to 1.2.
Homologues: Orthologues: chimpanzee SPDEF (99% identical), macaque SPDEF (97% identical), dog SPDEF (94% identical), pig SPDEF (93% identical), rat Spdef (87% identical), guinea pig SPDEF (86% identical), mouse Spdef (85% identical), tropical clawed frog spdef (67% identical), zebrafish SPDEF (63% identical), Drosophila melanogaster Ets98B (41% identical), Caenorhabditis elegans ets-4 (30% identical). Paralogues in human: ERG (25% identical), ETS1 (25% identical), ETS2 (25% identical), FLI1 (25% identical), GABPA (24% identical), ETV6 (22% identical), ETV5 (20% identical), ELF2 (20% identical), ETV7 (20% identical), ELF4 (19% identical), ETV1 (19% identical), ELF5 (19% identical), and 16 more.
Diseases named in the same sentence as SPDEF in open-access papers:
SPDEF is named in the same sentence as 64 diseases in open-access papers, as found by Europe PMC text mining. Sharing a sentence is not in itself a finding about the gene and the disease. The quoted sentences say what the papers report.
prostate carcinoma (50 papers, 2002 to 2025). A carcinoma that arises from epithelial cells of the prostate gland. "By analyzing the expression profiles of RNA biomarkers such as ERG, PCA3, and SPDEF in exosomes, this technology can effectively distinguish high-risk prostate cancer (Gleason score ≥ 7) from low-risk cases." (PMID 40277513, 2025). "This study aimed to evaluate the methylation status of a specific CpG dinucleotide (cg11346722) in the SPDEF gene promoter as a novel, cancer-specific epigenetic biomarker with both diagnostic and prognostic potential for prostate cancer." (PMID 40457266, 2025). "This study presents the first comprehensive evaluation of SPDEF gene CpG dinucleotide methylation as a potential epigenetic biomarker associated with prostate cancer (PCa) progression, defined by tumor stage and histological grade." (PMID 40457266, 2025). "To validate the association between SPDEF promoter methylation and gene expression in prostate cancer, we analyzed data from the TCGA PRAD cohort and publicly available GEO datasets." (PMID 40457266, 2025). "The data demonstrate that loss of SPDEF expression in prostate cancer cells, a critical step in cellular plasticity, results from a potentially reversible process of aberrant DNA methylation." (PMID 37900138, 2023). "Prostate cancer progression is associated with increased expression of DNMTs and a consequent increased methylation on SPDEF gene and subsequent decrease in SPDEF expression." (PMID 37900138, 2023). "Notwithstanding these discrepancies, given that SPDEF is a luminal-epithelial specific transcription factor, loss of SPDEF expression during prostate cancer progression suggests dedifferentiation away from luminal-epithelial phenotype and cellular plasticity." (PMID 37900138, 2023). "To more thoroughly investigate the association of SPDEF in PCa progression, we opted to analyze human clinical cohorts of prostate cancer." (PMID 37900138, 2023). "SPDEF is usually expressed in prostate epithelium, and higher expression levels are associated with prostate cancer and cancers of the brain, lung, breast, and ovaries." (PMID 30918060, 2019). "As a consequence of CDK11p58 mediated degradation of SPDEF, this loss of SPDEF protein results in increased prostate cancer cell migration and invasion." (PMID 26885618, 2016). "At the same time, the decrease in SPDEF expression was associated with transition from low-grade to high-grade human prostate cancer." (PMID 25254494, 2014). "It is possible that the loss of SPDEF causes increased expression of oncogenic Foxm1, accelerating tumor cell proliferation and leading to poor outcome in prostate cancer patients." (PMID 25254494, 2014). "In high-risk group of patients and in lethal prostate cancers, Foxm1 mRNA was significantly overexpressed while SPDEF mRNA was significantly decreased." (PMID 25254494, 2014). "Expression levels of SPDEF and Foxm1 were compared between indolent and lethal prostate cancers and high-risk and low-risk sample groups." (PMID 25254494, 2014). "Previous studies have implicated SPDEF in prostate cancer (PCa) progression and metastasis." (PMID 40457266, 2025). "For example, upregulation of SPDEF is associated with poor prognosis in prostate cancer, but it could also serve as a suppressor in colorectal cancer." (PMID 35983409, 2022). "Loss of SPDEF was associated with occurrence of aggressive high-grade prostate cancer." (PMID 28076331, 2017). "Our hypothesis is that a shift in SPDEF protein turnover is a key step in prostate cancer metastasis and that degradation of SPDEF initiates a cascade of events associated with metastatic spread of prostate cancer." (PMID 26885618, 2016). "To further investigate this, we utilized the TIMER2.0 database to examine the relationship between SPDEF expression and immune infiltration profiles in prostate cancer." (PMID 40457266, 2025).
prostate carcinoma (continued). "Specifically, research has demonstrated that SPDEF expression is inversely correlated with methylation at CpG dinucleotides within its gene in prostate cancer tissues." (PMID 40457266, 2025). "SPDEF CpG hypomethylation levels were significantly associated with both tumor stage (TS) and histological grade (ISUP) in prostate cancer patients (n = 180)." (PMID 40457266, 2025). "Significant positive correlations with both TS and grade support the potential prognostic relevance of SPDEF promoter CpG site in prostate cancer." (PMID 40457266, 2025). "Consistent with prior studies showing hypomethylation of SPDEF in LNCaP prostate cancer cells, our data point to significant epigenetic dysregulation of SPDEF in PCa." (PMID 40457266, 2025). "Our in-vitro and clinical cohort analysis of human prostate cancer suggest that decreased expression of SPDEF highly correlates with PCa disease progression." (PMID 37900138, 2023). "Like prostate cancer cell lines, we observed that methylation at CpG islands of the SPDEF gene in prostate cancer patient tissues is inversely correlated with SPDEF expression and the extent of methylation at the CpG sites." (PMID 37900138, 2023). "SPDEF also functions as a tumor suppressor in prostate cancer by inhibiting mRNA and protein levels of Foxm1, a transcription factor critical for tumor cell proliferation." (PMID 36809297, 2023). "Our investigation into the impact of siRNA-mediated targeting of DNMTs (NDMT1, DNMT3A, and DNMT3B) on SPDEF expression in prostate cancer cells has yielded valuable insights." (PMID 37900138, 2023). "This compelling evidence underscores the direct involvement of DNMTs in the regulatory machinery governing SPDEF expression in prostate cancer cells." (PMID 37900138, 2023). "In contrast to these studies, two reports observed increased expression of SPDEF protein in prostate cancer tissues compared to normal tissues and suggested that SPDEF overexpression was associated with aggressive prostate cancer." (PMID 37900138, 2023). "Our findings demonstrate that 5-Aza-dC-mediated reprogramming and SPDEF expression enhancement can be replicated in aggressive prostate cancer cell lines by depleting DNMT1." (PMID 37900138, 2023). "To investigate this, we studied the correlation of SPDEF expression levels with the DNA methyltransferase enzymes in the TCGA Prostate Cancer (PRAD) clinical cohort (n=568)." (PMID 37900138, 2023). "Expression of SPDEF is highly induced in prostate and breast cancer origin cell lines as opposed to other cancer types, suggesting the specificity of SPDEF to prostate cancer." (PMID 32680982, 2020). "SPDEF is also regulated by AR signalling in prostate cancer, which has both beneficial and potentially detrimental effects when AR signaling is inhibited by androgen deprivation therapy (ADT)." (PMID 30200227, 2018). "In prostate cancer, loss of SPDEF protein correlates with poor differentiation and worse patient outcome, which is also reflected in prostate cancer cell lines where more aggressive lines express lower SPDEF." (PMID 30200227, 2018). "Previous studies showed that SPDEF is required for CDH1 expression in prostate cancer cells and that SPDEF is a downstream target of TGFB1." (PMID 28076331, 2017). "Methylseleninic acid (MSA), a synthetic selenium compound, has been shown to induce expression of SPDEF in prostate cancer cells, which is in line with the findings of our study." (PMID 28076331, 2017). "SPDEF has been reported to be overexpressed and to promote tumor growth in breast, ovarian, and prostate cancers, while paradoxically SPDEF has also been reported to function as a tumor suppressor in breast, ovarian, prostate, and colon cancers." (PMID 28255028, 2017). "In previous studies, it was consistently shown that SPDEF inhibits cancer cell migration in vitro as well as prostate cancer metastasis in vivo." (PMID 28076331, 2017).
prostate carcinoma (continued). "Taken together with our findings, SPDEF has different roles in the regulation of androgen-sensitive and -insensitive prostate cancer cell proliferation." (PMID 27853318, 2016). "In this study we sought to gain new insights into the role phosphorylation and protein degradation plays in SPDEF-dependent effects on prostate cancer cell migration and invasion." (PMID 26885618, 2016). "Knockdown of AIbZIP, which is a direct target of SPDEF, suppressed the proliferation of prostate cancer cells, indicating that AIbZIP functions downstream of SPDEF as a major regulator of proliferation in these cells." (PMID 27853318, 2016). "We show that GADD45 α and γ, directly interact with CDK11p58 and thereby inhibit CDK11p58 activity, and consequentially SPDEF phosphorylation and degradation, ultimately reducing prostate cancer cell migration and invasion." (PMID 26885618, 2016). "Most importantly, reduced SPDEF expression.directly correlates with poor outcome in prostate cancer." (PMID 26885618, 2016). "Here we demonstrate that GADD45α overexpression inhibits CDK11p58 kinase activity and impedes SPDEF degradation mediated by CDK11p58, inhibiting prostate cancer cell migration and invasion." (PMID 26885618, 2016). "A review of published gene expression data, moreover, suggests that regulation of SPDEF expression correlates with GADD45α in LNCaP prostate cancer and MCF-7 breast cancer cells." (PMID 26885618, 2016). "The role of SPDEF in metastasis is further supported by the recent study showing that SPDEF knockdown in prostate cancer cells enhances and overexpression reduces survival of prostate cancer cells at distal sites and metastasis formation." (PMID 26885618, 2016). "In conclusion, we demonstrated that AIbZIP is upregulated by SPDEF acting downstream of AR in prostate cancer cells." (PMID 27853318, 2016). "The relevance of SPDEF downregulation for prostate cancer metastasis has been confirmed in xenograft models, supporting our previous conclusions." (PMID 26885618, 2016). "Our migration and invasion data shown here indicate that silencing CDK11p58 and consequent inhibition of SPDEF degradation reduce prostate cancer cell migration." (PMID 26885618, 2016). "GADD45α expression is repressed due to methylation, and reduced SPDEF expression directly correlates with poor outcome in prostate cancer." (PMID 26885618, 2016). "In contrast to SPDEF and GADD45α, CDK11p58 strongly increased prostate cancer migration and invasion." (PMID 26885618, 2016). "Our present findings provide both in vivo and in vitro support for tumor suppressive role of SPDEF in prostate cancer." (PMID 25254494, 2014). "Two studies had shown correlation between decreased expression of SPDEF and poor prognosis in prostate cancer." (PMID 25254494, 2014). "Altogether, these results indicate that SPDEF decreases proliferation and migration of prostate cancer cells through inhibition of Foxm1." (PMID 25254494, 2014). "In prostate cancer patients, the low SPDEF and high Foxm1 were found in most aggressive prostate tumors that were associated with poor prognosis." (PMID 25254494, 2014). "It was also shown that SPDEF expression is decreased during the transition from low-grade to high-grade prostate cancer." (PMID 25254494, 2014). "In advanced prostate cancer and prostate cancer-derived cell lines, SPDEF was either decreased or lost." (PMID 25254494, 2014). "The present study identified novel molecular mechanism of prostate cancer progression, providing a crosstalk between SPDEF tumor suppressor and Foxm1 oncogene." (PMID 25254494, 2014). "The present study identified novel crosstalk between SPDEF tumor suppressor and Foxm1 oncogene and demonstrated that this crosstalk is required for tumor cell proliferation during progression of prostate cancer in vivo." (PMID 25254494, 2014). "The combined two-gene signature of low SPDEF and high Foxm1 was a strong predictor of survival in prostate cancer patients." (PMID 25254494, 2014).
prostate carcinoma (continued). "In present study, we generated transgenic mice with the loss- or gain-of-function of SPDEF in prostate epithelium to demonstrate that SPDEF functions as tumor suppressor in prostate cancer." (PMID 25254494, 2014). "The recent literature regarding prostate cancer has demonstrated that SPDEF CpG island methylation can be reliably detected in peripheral blood through PCR-based assays, enabling a non-invasive and tumor-specific approach to supplement diagnostic and therapeutic management." (PMID 41228349, 2025). "Additionally, another study reported that both enhancer and promoter regions of the SPDEF gene undergo significant hypermethylation in aggressive prostate cancer cell models." (PMID 40457266, 2025). "Furthermore, treatment with DNA methyltransferase inhibitors, such as 5-Aza-dC, has been shown to restore SPDEF expression and reduce the invasive properties of prostate cancer cells." (PMID 40457266, 2025). "Other studies have similarly reported SPDEF overexpression in cancers including prostate cancer." (PMID 40457266, 2025). "Hypomethylation of a specific CpG dinucleotide in the SPDEF promoter may serve as a promising noninvasive blood-based biomarker for the early detection and clinical stratification of prostate cancer." (PMID 40457266, 2025). "In the complementary studies, we utilized small interfering RNA (siRNA) to selectively target pivotal DNA methyltransferases (DNMTs), including NDMT1, DNMT3A, and DNMT3B, with the primary objective of elucidating their roles in the modulation of SPDEF protein expression within prostate cancer cells." (PMID 37900138, 2023). "Because SPDEF expression is decreased during prostate cancer progression in patients and advanced PCa cell lines, we hypothesized that the SPDEF gene might be partially regulated via DNA hypermethylation." (PMID 37900138, 2023). "In addition, our analysis of gene expression in prostate cancer specimens in human prostate cancer datasets revealed that SPDEF mRNA expression is decreased during prostate cancer progression." (PMID 37900138, 2023). "Gene expression analyses revealed that SPDEF expression is decreased during prostate cancer progression, and there is a gradual decrease in SPDEF expression with increasing Gleason grade and a significant decrease during the transition from CRPC-Adeno to CRPC-NE." (PMID 37900138, 2023). "Moreover, we demonstrate that all three DNMT levels correlate with SPDEF at the mRNA level in the clinical data sets in prostate cancer tissues." (PMID 37900138, 2023). "Also, SPDEF is overexpressed in Prostate adenocarcinomas from TCGA cohort as compared to normal tissues both from TCGA and GTEx, supporting the role of SPDEF in prostate cancer progression and development." (PMID 32680982, 2020). "In summary, the regulation of protein degradation of SPDEF by CDK11p58 may be a crucial factor for inducing prostate cancer cell migration and invasion, with major consequences in prostate cancer metastasis and systemic dissemination." (PMID 26885618, 2016). "Some of these critical activities of GADD45α in prostate cancer may be mediated through its regulation of SPDEF protein stability." (PMID 26885618, 2016). "To further confirm that CDK11p58 enhances migration and invasion of prostate cancer cells by inducing degradation of SPDEF, a critical step in prostate cancer metastasis, we measured migration and invasion of DU145 cells overexpressing SPDEF in the absence or presence of CDK11p58." (PMID 26885618, 2016). "The potential role of the non-fusion epithelial-specific Ets factor, SPDEF, as prostate cancer tumor and metastasis suppressor recently emerged, demonstrating that SPDEF expression loss in advanced prostate cancer correlates with poor outcome." (PMID 26885618, 2016). "Based on these findings we tested the hypothesis that SPDEF and GADD45α and γ are functionally interconnected and overlap in their tumor suppressive roles in prostate cancer." (PMID 26885618, 2016).